PACSIN3 (protein kinase C and casein kinase substrate in neurons 3)
Description:
Plays a role in endocytosis and regulates internalization of plasma membrane proteins. Overexpression impairs internalization of SLC2A1/GLUT1 and TRPV4 and increases the levels of SLC2A1/GLUT1 and TRPV4 at the cell membrane. Inhibits the TRPV4 calcium channel activity (By similarity).
Synonyms: SDPIII; CMYO27
Tractability: Antibody: its Gene Ontology location is reachable by antibodies, with high confidence; UniProt places it where antibodies can reach, with medium confidence. PROTAC: ubiquitination databases record sites on it; its protein half-life has been measured.
Gene: Protein-coding gene on chromosome 11 (47,177,520 to 47,187,487, reverse strand). Ensembl gene ENSG00000165912.
Subcellular location: Cytoplasm; Cell membrane
Subcellular location (Human Protein Atlas): Cytosol; Plasma membrane
Pathways (Reactome):
Vesicle-mediated transport: Clathrin-mediated endocytosis
Gene Ontology:
Molecular function: identical protein binding; lipid binding; protein binding; calcium channel inhibitor activity; cytoskeletal protein binding; phospholipid binding
Biological process: plasma membrane tubulation; positive regulation of membrane protein ectodomain proteolysis; cytoskeleton organization; negative regulation of calcium ion transport; negative regulation of endocytosis; regulation of endocytosis
Cellular component: cytosol; extracellular exosome; cytoplasm; endosome; plasma membrane
Genetic constraint (gnomAD): Loss-of-function variants: 34 observed, 53.44 expected, observed/expected ratio (o/e) 0.64, 90% interval 0.48 to 0.85. The upper end of that interval is the gene's LOEUF score, 0.85, which puts it in group 3 of 6, group 1 being the genes least tolerant of losing a copy. Missense variants: 535 observed, 579.23 expected, observed/expected ratio (o/e) 0.92, 90% interval 0.86 to 0.99. Synonymous variants: 218 observed, 220.51 expected, observed/expected ratio (o/e) 0.99, 90% interval 0.88 to 1.11.
Homologues: Orthologues: chimpanzee PACSIN3 (100% identical), macaque PACSIN3 (100% identical), rabbit PACSIN3 (97% identical), dog PACSIN3 (96% identical), pig PACSIN3 (95% identical), mouse Pacsin3 (94% identical), rat Pacsin3 (94% identical), guinea pig PACSIN3 (94% identical), tropical clawed frog pacsin3 (67% identical), zebrafish pacsin3 (52% identical), Drosophila melanogaster Synd (41% identical), Caenorhabditis elegans sdpn-1 (32% identical). Paralogues in human: PACSIN2 (58% identical), PACSIN1 (52% identical).
Diseases named in the same sentence as PACSIN3 in open-access papers:
PACSIN3 is named in the same sentence as 15 diseases in open-access papers, as found by Europe PMC text mining. Sharing a sentence is not in itself a finding about the gene and the disease. The quoted sentences say what the papers report.
breast carcinoma (3 papers, 2008 to 2014). "New targets for breast cancer treatment were identified such as ZONAB, PACSIN3, MRP8 and SUMO1 which have human homologues." (PMID 18179684, 2008).
cardiac hypertrophy (1 paper, 2025). "Cardiomyocytes in PACSIN3 knockout mice lack caveolae, while its potential modifying function in cardiac hypertrophy remains to be elucidated." (PMID 40791945, 2025).
Cirrhosis (1 paper, 2025). A chronic disorder of the liver in which liver tissue becomes scarred and is partially replaced by regenerative nodules and fibrotic tissue resulting in loss of liver function. "For the other down-regulated genes, the majority have not been associated to NAFLD or cirrhosis development, including PACSIN3." (PMID 40489530, 2025). "Differential expression of COL4A4 and PACSIN3 was found in patients with NAFLD and cirrhosis compared to healthy individuals, and GSN, that is associated to HCC, was the most upregulated gene in cirrhosis." (PMID 40489530, 2025).
epilepsy (1 paper, 2025). A brain disorder characterized by episodes of abnormally increased neuronal discharge resulting in transient episodes of sensory or motor neurological dysfunction, or psychic dysfunction. "There were 8 proteins shared between epilepsy and ischemic stroke: SH3BGRL3, BPNT1, PTPMT1, PACSIN3, MIPEP, CMC2, ABCA5, and PTK2B." (PMID 40624693, 2025).
migraine (1 paper, 2023). "We also identified two additional genes, HNRNPK and PACSIN3, in the PWAS by integrating proteomics data from the Banner Sun Health Research Institute with migraine GWAS data." (PMID 37592229, 2023).
tuberculosis (1 paper, 2024). A chronic, recurrent infection caused by the bacterium Mycobacterium tuberculosis. "The results of ROC showed that TYMP (AUC = 0.964), LAP3 (AUC = 0.914), ADGRL2 (AUC = 0.98), SIL1 (AUC = 0.936), LMO7 (AUC = 0.856), SULF1 (AUC = 0.96), ANXA3 (AUC = 0.798), and PACSIN3 (AUC = 0.747) had high accuracy in predicting tuberculosis." (PMID 39023413, 2024).
genetic muscular disorders (1 paper, 2022). "PACSIN3 is abundant in muscle tissue and necessary for caveolar biogenesis to create membrane reservoirs, thus controlling muscle function, and has been linked to certain genetic muscular disorders." (PMID 34990060, 2022).
PACSIN3 also shares sentences with these, for which no sentence is quoted: cardiomyopathy (1 paper); caveolinopathies (1); centronuclear myopathy (1); fibrosarcoma (1); infection (1); ischemic stroke (1); myopathies (1); tumor (1).